TMEM260 (transmembrane protein 260)
Description:
O-mannosyl-transferase that transfers mannosyl residues to the hydroxyl group of serine or threonine residues of proteins. Specifically glycosylates the IPT/TIG domain of target proteins, such as MET and MST1R/RON. TMEM260-mediated O-mannosylated residues are composed of single mannose glycans that are not elongated or modified.
Synonyms: C14orf101; FLJ20392; SHDRA
Tractability: Antibody: UniProt predicts a signal peptide or a membrane-spanning region. PROTAC: its protein half-life has been measured.
Gene: Protein-coding gene on chromosome 14 (56,488,354 to 56,650,606, forward strand). Ensembl gene ENSG00000070269.
Subcellular location: Endoplasmic reticulum membrane; Membrane (Isoform 3)
Gene Ontology:
Molecular function: dolichyl-phosphate-mannose-protein mannosyltransferase activity
Biological process: protein maturation; protein O-linked glycosylation via mannose
Cellular component: endoplasmic reticulum membrane; membrane
Genetic constraint (gnomAD): Loss-of-function variants: 53 observed, 63.52 expected, observed/expected ratio (o/e) 0.83, 90% interval 0.67 to 1.05. The upper end of that interval is the gene's LOEUF score, 1.05, which puts it in group 4 of 6, group 1 being the genes least tolerant of losing a copy. Missense variants: 731 observed, 691.65 expected, observed/expected ratio (o/e) 1.06, 90% interval 0.99 to 1.12. Synonymous variants: 273 observed, 259.23 expected, observed/expected ratio (o/e) 1.05, 90% interval 0.95 to 1.16.
Homologues: Orthologues: chimpanzee TMEM260 (99% identical), macaque TMEM260 (98% identical), dog TMEM260 (91% identical), pig TMEM260 (91% identical), rabbit TMEM260 (87% identical), guinea pig TMEM260 (86% identical), rat Tmem260 (83% identical), mouse Tmem260 (82% identical), tropical clawed frog tmem260 (61% identical), zebrafish tmem260 (48% identical).
Diseases named in the same sentence as TMEM260 in open-access papers:
TMEM260 is named in the same sentence as 10 diseases in open-access papers, as found by Europe PMC text mining. Sharing a sentence is not in itself a finding about the gene and the disease. The quoted sentences say what the papers report.
structural heart defects and renal anomalies syndrome (3 papers, 2022 to 2024). "Among five patients, we identified pathogenic variants in TMEM260; the biallelic loss-of-function variants of which have recently been associated with structural heart defects and renal anomalies syndrome (SHDRA)." (PMID 38351237, 2024). "Subsequently, our team consulted with international expert groups and the case (Family 5) was acknowledged and published as new evidence to expand the mutation spectrum of TMEM260 biallelic variants in association with structural heart defects and renal anomalies syndrome (SHDRA)." (PMID 36554045, 2022). "Phenotype of patients with c.1617del appears to be predominantly in the heart, although TMEM260 is responsible for structural heart defects and renal anomalies syndrome (SHDRA)." (PMID 38409496, 2024).
Truncus arteriosus (3 papers, 2022 to 2024). A single arterial trunk arises from the cardiac mass. "We reported that the pathogenic variant c.1617del of TMEM260, which encodes a transmembrane protein, is highly associated with CHD, specifically persistent truncus arteriosus (PTA), the most severe cardiac outflow tract (OFT) defect." (PMID 38409496, 2024). "In one quad analysis in which the ultrasonography of both fetuses (proband and prior pregnancy) showed truncus arteriosus, we identified and reported two compound heterozygous VUS variants on TMEM260 (Transmembrane protein 260), and the parents were carriers." (PMID 36554045, 2022).
developmental delays (1 paper, 2024). "In particular, Patient 3, at 29 years of age, is the oldest patient with TMEM260 variants reported to date and has not only had no renal dysfunction but also has no noted developmental delays, graduated from university, and works as a caregiver." (PMID 38351237, 2024).
microcephaly (1 paper, 2025). A congenital or acquired developmental disorder in which the circumference of the head is smaller than normal for the person's age and sex. "Another feature of AM is macrocephaly; however, Patient 3.1 experienced microcephaly due to concurrent genetic diseases, structural heart defects, and renal anomalies (OMIM: 617478, TMEM260)." (PMID 39926434, 2025).
renal dysfunction (1 paper, 2024). "In contrast, among the patients harboring TMEM260 variants in this study, four of the five survived from 6 to 29 years of age without any signs of renal dysfunction." (PMID 38351237, 2024).
genetic diseases (2 papers, 2024 to 2025). "Taken together, we speculate that the c.1617del variant of TMEM260 might be a founder variant for PTA in Japan or East Asia because it is responsible for rare genetic disorders, usually resulting from recessive alleles, with a relatively high frequency in specific populations." (PMID 38409496, 2024).
TMEM260 also shares sentences with these, for which no sentence is quoted: 22q11.2 deletion syndrome (1 paper); cardiac disease (1); congenital heart disease (1); non-Hodgkin lymphoma (1).